TNC (tenascin C)
Diseases named in the same sentence as TNC in open-access papers (continued):
Sharing a sentence is not in itself a finding about the gene and the disease.
Hepatitis (3 papers, 2016 to 2024). Inflammation of the liver. "Knockout of TNC in a hepatitis mouse model attenuated fibrotic and inflammatory responses in the liver." (PMID 37899138, 2023).
Insulin resistance (3 papers, 2017 to 2022). Increased resistance towards insulin, that is, diminished effectiveness of insulin in reducing blood glucose levels. "This is important because chronic inflammation in obese individuals is associated with muscle insulin resistance, and it could be hypothesised that the tenascin-C/TLR4 signalling axis is also involved in this response." (PMID 29137117, 2017). "Tenascin-C (TNC), an extracellular matrix glycoprotein, is elevated in inflammatory and cardiovascular pathologies, whereas alarin, a novel orexigenic peptide, participates in insulin resistance and glycometabolism." (PMID 35493201, 2022). "Tenascin C, as a glycoprotein member of ECM, is related to tissue developmental processes, while miR-145 is involved in abdominal obesity, insulin resistance, and lipid metabolism." (PMID 32485856, 2020).
ischemic stroke (3 papers, 2021 to 2023). A stroke disorder caused by obstruction of blood flow to the brain, due to thrombotic (local blood clot formation) or embolic (due to a blood clot or other material traveling from another site) event. "A recent investigation showed neuroprotection, reduction in infarct sizes, protection of the BBB, improved motor functions and increased survival upon siRNA-mediated knockdown of tenascin C in experimental ischemic stroke." (PMID 34572077, 2021). "Findings from ischemic stroke studies have highlighted that specific ECM components including CSPGs, fibronectin, thrombospondin, tenascin-C and laminins are elevated and exacerbate injury by enhancing neuroinflammation in the perihematomal area." (PMID 38025264, 2023).
mesothelioma (3 papers, 2011 to 2023). A usually malignant and aggressive neoplasm of the mesothelium which is often associated with exposure to asbestos. "We have previously reported that Tenascin C, a modulator of cell invasive potential, is upregulated in mesothelioma cells primed in cell culture conditions conducive to TNT formation." (PMID 37955637, 2023).
Myocardial fibrosis (3 papers, 2021 to 2024). "In vivo studies have shown that TNC deficiency can reduce experimental inflammatory diseases such as angiotensin II-induced myocardial fibrosis." (PMID 34124185, 2021). "In addition, PIEZO1 activated by Yoda1 may also increase tenascin C (TNC) expression to promote myofibroblast differentiation and ultimately induce myocardial fibrosis." (PMID 39272994, 2024).
psoriasis (3 papers, 2022 to 2024). An autoimmune condition characterized by red, well-delineated plaques with silvery scales that are usually on the extensor surfaces and scalp. "Secondly, the activation of fibroblasts in skin diseases remains not entirely understood, despite previous work by Cai and colleagues, who observed inflammation-induced TNC overexpression in fibroblasts in a psoriasis mouse model." (PMID 39009587, 2024). "TNC has been reported to be expressed throughout the skin basement membrane in psoriasis and several other hyperproliferative skin diseases, remaining abundant after clinical lesion remission;34,37,47 with its functions uncharacterized." (PMID 37037861, 2023). "TNC overexpression in fibroblasts boosts neurite outgrowth in co-cultured neurons, while fibroblast-specific TNC ablation suppresses hyperinnervation and alleviates skin inflammation in male mice modeling psoriasis." (PMID 37037861, 2023).
skin tumor (3 papers, 2020 to 2022). "In human skin cancer, a splicing alteration in the protein TNC (tenascin C) pre-mRNA increases the number of tumor-promoting TNC-FL isoforms, resulting in cancer cell invasion and metastasis." (PMID 33407694, 2021). "However, TNC expression is significantly elevated in the dermal compartment during wound healing and in skin tumors." (PMID 33217999, 2020). "However, according to our data, the Itga11-/- skin tumor CAFs do not respond as efficiently to TGFβ1 induction as the control CAFs, as demonstrated by the downregulation of fibrillar collagen and TNC biosynthesis in the knockout tumors." (PMID 36003785, 2022). "Our attempts to establish CAF lines from Itga11-/- skin tumors using either the explant method or anti-PDGFRα antibody-based FACS were not successful, and thus, the functions and molecular mechanisms involving α11, PDGFRβ and TNC could not be studied further under in vitro conditions." (PMID 36003785, 2022).
systemic lupus erythematosus (3 papers, 2015 to 2024). An autoimmune multi-organ disease typically associated with vasculopathy and autoantibody production. "The aim of this study was to examine whether circulating levels of the proinflammatory glycoprotein tenascin-C (TNC) are useful as an activity-specific or predictive biomarker in systemic lupus erythematosus (SLE)." (PMID 26608564, 2015).
triple-negative breast carcinoma (3 papers, 2016 to 2021). An invasive breast carcinoma which is negative for expression of estrogen receptor (ER), progesterone receptor (PR), and human epidermal growth factor receptor 2 (HER2). "As a secreted cellular matrix protein, tenascin-C inhibits T cell activation, but SKP2 induces tenascin-C ubiquitination and p62-mediated autophagic degradation, in contrast, autophagy deficiency reverses this event resulting in (TNBC) triple-negative breast cancer resistance to T cell." (PMID 34493296, 2021).
viral infection (3 papers, 2019 to 2022). "In addition to high levels of expression in tumors, and during chronic inflammation, and bacterial and viral infection, TNC is also expressed in lymphoid organs." (PMID 36102918, 2022).
abdominal aortic aneurysm (2 papers, 2021 to 2022). Enlargement and ballooning of the vessel that supplies arterial blood to the abdomen, pelvis and legs. "Up-regulation of tenascin C (TNC), a matricellular protein, produced mainly by vascular smooth muscle cells (VSMC), is associated with the progression and dilation of abdominal aortic aneurysms (AAA)." (PMID 35137102, 2022).
acute coronary syndrome (2 papers, 2020 to 2025). Signs and symptoms related to acute ischemia of the myocardium secondary to coronary artery disease. "Increased expression of TNC leads to rupture of plaques, thrombus formation, occlusion of coronary arteries and acute coronary syndrome." (PMID 33312062, 2020). "Hence, the study aimed to understand the association between serum tenascin-C, GDF-15 levels and risk of the acute coronary syndrome among T2DM patients." (PMID 33312062, 2020). "Furthermore, some authors propose that TnC could be a useful marker for predicting the severity of an acute coronary syndrome." (PMID 41010873, 2025).
acute kidney injury (2 papers, 2022 to 2026). Sudden and sustained deterioration of the kidney function characterized by decreased glomerular filtration rate, increased serum creatinine or oliguria. "Previous analyses showed that Tenascin-C (TNC) was associated with acute kidney injury; however, its correlation with DGF is unclear." (PMID 41782890, 2026).
allergic asthma (2 papers, 2005 to 2011). A asthma with a basis in a pathological type I hypersensitivity reaction. "Surprisingly, however, the OVA-challenged STAT4-/- mice showed no increase in tenascin-C mRNA production after allergen challenge, suggesting that STAT4 is an important regulator of tenascin-C in acute allergic asthma." (PMID 21205293, 2011). "We investigated whether one of these two distinct parts of adaptive immunity, Th1 or Th2, might play an independent role in the regulation of tenascin-C expression in experimental allergic asthma in the lung." (PMID 21205293, 2011). "Previous studies have demonstrated that prolonged allergic asthma may lead to structural changes in the airways, which include the modification of extracellular matrix proteins such as tenascin-C." (PMID 21205293, 2011). "In this study, we examined whether Th1 or Th2 cells are important regulators of tenascin-C in experimental allergic asthma utilizing mice with impaired Th1 (STAT4-/-) or Th2 (STAT6-/-) immunity." (PMID 21205293, 2011). "To test whether Th1 or Th2 cells are important regulators of tenascin-C expression in experimental allergic asthma, we studied the responses of mice with impaired Th1 (STAT4-/-) or Th2 (STAT6-/-) immunity." (PMID 21205293, 2011).
aortic valve calcification (2 papers, 2021 to 2022). "Among DEGs not related to humoral immunity many overlap with those already implicated in aortic valve calcification, these include TNC, PRG4, COL11A1, SMOC2, FN1, and OGN." (PMID 36437309, 2022). "The expression of SPP1, TNC, SCG2, FAM20A, and CD52 was all significantly up-regulated in calcific aortic valve disease." (PMID 34020624, 2021).
atopic asthma (2 papers, 2011 to 2012). An asthma that is characterized by symptoms that are triggered by an allergic reaction caused by inhaled allergens such as dust mite allergen, pet dander, pollen and mold. "Tenascin C is implicated in allergies and increases during seasonal atopic asthma." (PMID 23148572, 2012).
bullous keratopathy (2 papers, 2012 to 2022). "Regarding the cornea, earlier publications reported higher tenascin-C level in bullous keratopathy, keratoconus, and its role has been demonstrated in corneal inflammation, fibrosis, scarring, neovascularization, and wound healing." (PMID 36294311, 2022). "Prior reports have described excessive tenascin-C expression in the epithelium, basement membrane, subepithelial layer, and posterior stroma in bullous keratopathy." (PMID 36294311, 2022). "Tenascin-C immunopositivity in inflammation, active scarring, angiogenesis and bullous keratopathy have been documented." (PMID 22876117, 2012).
cataract (2 papers, 2018 to 2021). Partial or complete opacity of the crystalline lens of one or both eyes that decreases visual acuity and eventually results in blindness. "Similarly, when compared with the control group (patients with cataracts who did not have pseudoexfoliation), tenascin C values in both the aqueous humor and blood were significantly high in the PEX group." (PMID 30116633, 2018).
cholangiocarcinoma (2 papers, 2018 to 2020). A carcinoma that arises from the intrahepatic biliary tree (intrahepatic cholangiocarcinoma) or from the junction, or adjacent to the junction, of the right and left hepatic ducts (hilar cholangiocarcinoma). "Interestingly, in addition to NHL, tenascin-C expression has been previously reported also in the cytoplasm of neoplastic cells of several solid tumors such as breast, laryngeal or cholangiocarcinomas." (PMID 29515769, 2018). "Here we examined intrahepatic cholangiocarcinomas (n = 8), carcinomas of perihilar bile ducts (n = 7), carcinomas of the gallbladder (n = 11) and hepatic metastasis from carcinomas of the gallbladder (n = 4) for the expression of the extracellular matrix glycoproteins tenascin-C and tenascin-W." (PMID 33692777, 2020).
Cirrhosis (2 papers, 2013 to 2025). A chronic disorder of the liver in which liver tissue becomes scarred and is partially replaced by regenerative nodules and fibrotic tissue resulting in loss of liver function. "A tenascin C splice variant is expressed in both pulmonary fibrosis, including in our human IPF samples, and cirrhosis, and may serve as a biomarker for cirrhosis." (PMID 23844188, 2013).
collagenous colitis (2 papers, 2022 to 2023). A type of microscopic colitis of unknown etiology. "This subepithelial collagen band coincides with the localization of the basal apical mucosal tenascin-C staining which is shown to be significantly increased in collagenous colitis patients." (PMID 35669358, 2022).
diabetic cardiomyopathy (2 papers, 2022 to 2023). Diabetic cardiomyopathy is a disorder of the heart muscle in people with diabetes. "We speculate that Tenascin C levels may not drive development of fibrosis in early diabetic cardiomyopathy and may not be sensitive markers for identifying alterations at this stage of disease." (PMID 35587779, 2022). "Importantly, TNC KOdiabetic mice did not induce wall thickness alterations, suggesting the pivotalrole of TNC in diabetic maladaptive coronary artery remodeling which is moreattenuated during the progression of diabetic cardiomyopathy." (PMID 39076867, 2023).
epilepsy (2 papers, 2019 to 2025). A brain disorder characterized by episodes of abnormally increased neuronal discharge resulting in transient episodes of sensory or motor neurological dysfunction, or psychic dysfunction. "The ROC curves revealed that the expression levels of key genes NCAM1, CPVL, PECAM1, and TNC had high accuracy in classifying epilepsy and control groups (AUC >0.9)." (PMID 40520613, 2025). "Given both the enrichment in Epi4k probands for CH variants in these genes as well as their known involvement in neuronal processes, we suggest that PRTG, TNC and MACF1 are candidate recessive epilepsy genes." (PMID 31190668, 2019). "PRTG, TNC and MACF1 are candidate recessive epilepsy genes and our work highlights that inheritance of CH variants should not be excluded from gene discovery or diagnostic analyses of patients with epilepsy." (PMID 31190668, 2019). "However, PRTG, TNC and MACF1 are potential novel recessive epilepsy genes and our results highlight that compound heterozygous variants should be considered in sporadic epilepsy." (PMID 31190668, 2019).
esophageal adenocarcinoma (2 papers, 2001 to 2017). A malignant tumor with glandular differentiation arising predominantly from Barrett mucosa in the lower third of the esophagus. "Increased tenascin-C expression is associated with metastasis and poor prognosis in esophageal adenocarcinoma." (PMID 28978001, 2017). "In addition, the results show that high tenascin-C expression in tumor stroma associates with advanced disease and reduced survival, and could therefore be used as a biomarker for esophageal adenocarcinoma with poor prognosis." (PMID 28978001, 2017). "Tenascin-C and fibronectin were stained immunohistochemically and assessed in esophageal specimens from patients with esophageal adenocarcinoma (n=90) or dysplasia (n=30)." (PMID 28978001, 2017). "Tenascin-C and fibronectin are upregulated in esophageal adenocarcinoma when compared to Barrett’s esophagus and dysplasia." (PMID 28978001, 2017). "The aim of this study was to evaluate the expression of tenascin-C and fibronectin in esophageal adenocarcinoma and its precursor stages." (PMID 28978001, 2017). "Stromal expression of tenascin-C in normal mucosa was higher than in Barrett’s esophagus or dysplasia, and nearly similar compared to adenocarcinoma." (PMID 28978001, 2017). "Based on our results, tenascin-C expression is upregulated in stroma of esophageal adenocarcinoma when compared to gastric and intestinal metaplasia and low- and high-grade dysplasia." (PMID 28978001, 2017). "We demonstrate the expression of tenascin-C and fibronectin in normal esophageal mucosa and in columnar metaplasia-dysplasia-adenocarcinoma-sequence of Barrett’s esophagus." (PMID 28978001, 2017). "A single study has reported no expression of tenascin-C in 6 patients with Barrett’s esophagus and upregulation of tenascin-C in 15 patients with esophageal adenocarcinoma, showing association to poor tumor differentiation." (PMID 28978001, 2017). "In conclusion, our results indicate that both tenascin-C and fibronectin are highly expressed in the stroma of esophageal adenocarcinoma and that expression in the precursor stages, including Barrett’s esophagus and dysplasia, is low compared to the cancer tissue." (PMID 28978001, 2017). "The aim of the study was to determine the expression of tenascin-C and fibronectin in esophageal adenocarcinoma and its precursor stages, and to evaluate if the molecules could be used as prognostic factors or as biomarkers of premalignant lesions." (PMID 28978001, 2017). "Our results indicate that matrilysin is the principal MMP expressed by tumour cells in oesophageal adenocarcinoma, and further studies are needed to investigate whether matrilysin or tenascin-C could be used as a predictive marker for progression of BE to cancer." (PMID 11487270, 2001). "No published information on tenascin-C or fibronectin in esophageal adenocarcinoma or its precursor stages could be found in larger patient cohorts." (PMID 28978001, 2017).
head and neck cancer (2 papers, 2011 to 2017). A primary or metastatic malignant neoplasm affecting the head and neck. "It promotes migration and invasion and high expression of TNC has been shown to predict poor clinical outcome in head and neck cancer." (PMID 29202741, 2017). "In this article, we report the first comparative analysis of expression patterns for the extra domains EDB and EDA of fibronectin and A1 of tenascin-C in both primary and metastatic head and neck cancer lesions." (PMID 21548989, 2011). "The majority of head and neck cancer types exhibited a diffuse pattern of expression for splice isoforms of fibronectin and of tenascin-C." (PMID 21548989, 2011).
hypertensive heart disease (2 papers, 2020 to 2022). Abnormal enlargement of the heart resulting from long-standing hypertension. "In accordance, alterations in the serum levels of MMP-9 and Tenascin-C variants reflecting myocardial tissue remodelling have been recently described in hypertensive heart disease." (PMID 32545310, 2020).
hypertrophic cardiomyopathy (2 papers, 2014 to 2024). A condition in which the myocardium is hypertrophied without an obvious cause. "Cardiac TnI mutation R145G found in familial hypertrophic cardiomyopathy is within the inhibitory region and alters the interaction of cardiac TnI with cardiac TnC." (PMID 24817852, 2014). "However, mutations in TnT, TnI, and TnC can also cause hypertrophic cardiomyopathy, and one particular mutation in TnI has been shown to cause both restrictive or hypertrophic cardiomyopathy." (PMID 39282088, 2024). "Mutations in cardiac/slow TnC account for approximately 0.4% of hypertrophic cardiomyopathy." (PMID 24817852, 2014).
influenza (2 papers, 2021 to 2025). An acute viral infection of the respiratory tract, occurring in isolated cases, in epidemics, or in pandemics; it is caused by serologically different strains of viruses (influenzaviruses) designated A, B, and C, has a 3-day incubation period, and usually lasts for 3 to 10 days. "Here we have focused on recently identified T-cell epitopes from citrullinated Tenascin C, to which T cells have been found to be prevalent, in some cases in close parity to that of virus-specific (influenza) T cells." (PMID 34972837, 2021). "The top-ranked genes for influenza classification included IFI27, ZFP36L1, TNC, SERTAD2, and AMPD3, several of which are known interferon-stimulated or antiviral response genes." (PMID 41020849, 2025).
invasive ductal breast carcinoma (2 papers, 2016 to 2021). The most common type of invasive breast carcinoma, accounting for approximately 70% of breast carcinomas. "According to the Ingenuity Pathways Knowledge Base, the “disease and function annotation” analysis for the DEPs from MPT x MLN tissues comparison indicated only the POSTN and TNC genes as involved in the invasive ductal breast carcinoma." (PMID 33656060, 2021).
Kawasaki disease (2 papers, 2021 to 2022). A rare inflammatory disease characterized by an acute febrile, systemic, self-limiting, medium-vessel vasculitis primarily affecting children. "Our previous retrospective study conducted in 2016 revealed that the serum tenascin-C level was higher in patients with Kawasaki disease (KD) who were resistant to intravenous immunoglobulin (IVIG) and developed coronary artery lesions (CALs)." (PMID 34090475, 2021).
kidney carcinoma (2 papers, 2012 to 2022). Primary or metastatic malignant neoplasm involving the kidney. "TNW and TNC expression was analyzed by western-blotting in kidney carcinoma samples, and their amounts were estimated by the intensity of the corresponding bands." (PMID 22947174, 2012).